RN7SL313P (RNA, 7SL, cytoplasmic 313, pseudogene)
Gene: Miscellaneous RNA gene on chromosome 2 (97,100,587 to 97,100,874, forward strand). Ensembl gene ENSG00000275655.
Homologues: Orthologues: chimpanzee Metazoa_SRP (99% identical), macaque Metazoa_SRP (74% identical). Paralogues in human: RN7SL210P (96% identical), RN7SL1 (84% identical), RN7SL2 (83% identical), RN7SL3 (82% identical), RN7SL45P (82% identical), RN7SL566P (82% identical), RN7SL296P (81% identical), RN7SL597P (81% identical), RN7SL230P (80% identical), RN7SL278P (80% identical), RN7SL441P (80% identical), RN7SL113P (80% identical), and 704 more.